PSG10P (pregnancy specific beta-1-glycoprotein 10, pseudogene)
Synonyms: formerly PSG12; PSG10
Gene: Transcribed unprocessed pseudogene on chromosome 19 (42,844,357 to 42,855,619, reverse strand). Ensembl gene ENSG00000248257.
Diseases named in the same sentence as PSG10P in open-access papers:
PSG10P is named in the same sentence as 1 disease in open-access papers, as found by Europe PMC text mining. Sharing a sentence is not in itself a finding about the gene and the disease.
PSG10P shares sentences with these, for which no sentence is quoted: preeclampsia (1 paper).